HNF1B (HNF1 homeobox B)
Diseases named in the same sentence as HNF1B in open-access papers (continued):
Sharing a sentence is not in itself a finding about the gene and the disease.
MODY (continued). "The most common subtypes of MODY are associated with mutations in the genes GCK, HNF1A, HNF4A, and HNF1B; among them, up to 70% of cases are caused by mutations in GCK and HNF1A." (PMID 33477506, 2021). "HNF1B was first reported as a potential candidate gene for MODY although extensive research indicated it as an important gene having a role in tumorigenesis." (PMID 33580750, 2021). "The most common forms of MODY are caused by mutations in the glucokinase gene (GCK-MODY) and hepatocyte nuclear factor genes (HNF1A-, HNF1B- and HNF4A-MODY) which together are responsible for around 99% of all MODY cases." (PMID 34299172, 2021). "Most cases of MODY are due to mutations in GCK, HNF1a, HNF4a and HNF1b, previously known as MODY2, MODY3, MODY1, and MODY5, respectively." (PMID 33259036, 2021). "After genetic analysis, diabetics (n = 46) with HNF1A, HNF1B, HNF4A, GCK gene mutations (diagnosed as MODY) and diabetics (n = 30) with HNF1B, HNF4A, GCK gene SNPs were excluded." (PMID 31109344, 2019). "A total of 4.1% of individuals had likely pathogenic or pathogenic variants in the commonest MODY genes (HNF1A, HNF4A, HNF1B, GCK or INS)." (PMID 30377832, 2018). "Patients with HNF1B-MODY require insulin treatment as the response to sulfonylureas and other oral medication is limited." (PMID 28314945, 2017). "Approximately 10% of MODY cases are from mutations in hepatocyte nuclear factor 4A (HNF4A) (MODY1) and hepatocyte nuclear factor 1B (HNF1B) (MODY5)." (PMID 26059258, 2016). "In our primary group, none of the MODY patients was obese, whereas in the UK one single patient with HNF1B-MODY crossed the 30 kg/m2 threshold of BMI." (PMID 27059371, 2016). "Mutations in genes like pancreatic and duodenal homeobox 1 (PDX1, MODY4), hepatocyte nuclear factor 1 beta (HNF1B, MODY5) neurogenic differentiation 1 (NEUROD1, MODY6) and insulin (INS, MODY10) cause relatively rare forms of MODY." (PMID 26300908, 2015). "In many MODY-associated TF genes, homozygous LOF variants are generally thought to be embryonically lethal or result in early mortality, e.g., in GATA4, GATA6, HNF1A, HNF1B, HNF4A, and ONECUT1." (PMID 41356216, 2025). "Our findings align with those of a study of 224 MODY patients in Turkey, where mutations were identified in the following proportions: 65% in the GCK gene, 19% in HNF1A, 3.6% in HNF4A, 3.6% in KLF11, and 3.1% in HNF1B." (PMID 39859454, 2025). "Even in HNF1B-MODY, where insulin is often the default, incretin therapy has shown promise: semaglutide has enabled insulin withdrawal, improved time-in-range, and modest weight loss, while tirzepatide has increased fasting C-peptide and dramatically reduced insulin needs." (PMID 41262822, 2025). "Of the 10 known MODY-associated TF genes, the three most common ones alone are estimated to account for more than two-thirds of all MODY cases: HNF1A (52%), HNF4A (10%), and HNF1B (6%)." (PMID 41356216, 2025). "Furthermore, GCK-MODY and HNF1B-MODY were the two next most common subtypes of MODY in the TCGS cohort study respectively." (PMID 39191897, 2024). "Therefore, regular screening for retinopathy and nephropathy in individuals with MODY, especially with variants in HNF4A, HNF1A, and HNF1B, is recommended." (PMID 39511990, 2024). "The correct molecular diagnosis in this case was critical to the patient, who could then be maintained on insulin therapy in addition to undergoing follow-up of her early-onset renal dysfunction and electrolyte disturbances characteristic of HNF1B MODY." (PMID 39420905, 2024). "HNF1B-MODY may have a higher prevalence in certain populations and ethnic groups; some studies have suggested a higher prevalence in populations of European ancestry." (PMID 37511676, 2023). "However, further research is necessary to elucidate the underlying mechanisms and establish clearer genotype–phenotype correlations in HNF1B-related MODY." (PMID 37511676, 2023). "Genetic counseling plays a crucial role in the management of HNF1B-related MODY." (PMID 37511676, 2023).
MODY (continued). "Despite being a rare disease, HNF1B-MODY is underdiagnosed and often misclassified." (PMID 36793123, 2023). "Seven patients (three females) from five families were identified to have HNF1B-related MODY." (PMID 37511676, 2023). "HNF1B-related MODY results in the dysfunction of multiple organ systems." (PMID 37511676, 2023). "Mutations in GCK, HNF1A, HNF1B, and HNF4A account for approximately 80% of the MODY cases." (PMID 37941991, 2023). "Regarding the treatment of HNF1B/MODY, patients present hepatic insulin resistance to some extent, and thus the treatment with oral hypoglycemic agents such as sulfonylureas may not be satisfactory, and early insulin therapy may be requested." (PMID 36672242, 2023). "HNF1B-MODY is very rare and constitutes 1–5% cases of all MODY patients." (PMID 35179657, 2022). "HNF1B mutations were also common in patients with suspected MODY but lacking renal features suggestive of HNF1B disease." (PMID 34789499, 2022). "Similarly, an UK study demonstrated that the mutation pick-up rate of MODY genes (HNF1A, HNF4A, HNF1B, or GCK) in South Asian participants was 12.6%, lower than White European group (25.2%)." (PMID 35921062, 2022). "LPA contributes to the pathogenesis of HNF1B-MODY by affecting Wnt/GSK-3 signaling." (PMID 35179657, 2022). "Concerning the others MODY subtypes, we found one variant in each HNF4A, HNF1B, and MT-TL1." (PMID 35592779, 2022). "The most common transcription factors that cause MODY when mutated belong to the hepatocyte nuclear factor (HNF) family (HNF4A, HNF1A and HNF1B), resulting in MODY1, MODY3 and MODY5, respectively, but other causal transcription factor genes have also been described." (PMID 34440499, 2021). "The rarity of our case lies in the fact that HNF1b/MODY is generally diagnosed in young adults, when disease-associated complications may already have developed." (PMID 33259036, 2021). "Alternatively, other genes implicated in the pathogenesis of MODY could be more frequent in these groups, such as HNF4A, insulin promoter factor-1 (IPF-1), HNF1B, NeuroD1 and others." (PMID 31576961, 2020). "Interestingly, Japanese monozygotic twins with MODY 5, both of whom displayed a microdeletion of 17q12 including HNF1B, exhibited malformation of the pancreas and kidneys, hypomagnesaemia, and hyperuricemia." (PMID 32871938, 2020). "Similarly, prioritizing GCK or HNF1B sequencing should be considered in probands, who present distinct clinical features of these MODY forms." (PMID 30778899, 2019). "This patient had no other MODY candidate variants, suggesting that the loss of one copy of HNF1B is responsible for the phenotype." (PMID 29439679, 2018). "The majority of MODY cases are accounted for by mutations in one of four genes: the transcription factors, hepatocyte nuclear factor 1-alpha (HNF1A), 4-alpha (HNF4A), 1-beta (HNF1B) and the enzyme, glucokinase (GCK)." (PMID 30377832, 2018). "To analyze the frequencies of the carriers of such mutations in our cohort, we analyzed genes (HNF1A, HNF4A, HNF1B, INS, ABCC8, and KCNJ11) in which a significant number of missense mutations have previously been reported in MODY, neonatal diabetes mellitus, or early onset diabetes." (PMID 29207974, 2017). "The most commonly mutated genes in MODY are HNF1A and GCK, followed by HNF4A and HNF1B." (PMID 29207974, 2017). "Similarly, several MODY-associated genes, including GCK, HNF1A and HNF1B, are important for maintaining normal hepatic function." (PMID 27185732, 2016). "The HNF1B gene causing MODY5 was not sequenced because of the distinct clinical presentation of this form of MODY." (PMID 19216786, 2009). "Besides, almost half of MODY patients have the HNF1B whole gene deletion." (PMID 38957807, 2024).
MODY (continued). "Among the six detected motifs, four were highly similar to the known consensus motifs HNF1B (P = 10−38), NEUROG2 (P = 10−32), FOXA1 (P = 10−23), and RFXDC2 (P = 10−15), among which HNF1B is known to be responsible for maturity-onset diabetes of the young (MODY) type 5." (PMID 38876803, 2024). "It is important to note that, while these extrapancreatic manifestations are associated with HNF1B-related MODY, not all patients with HNF1B mutations will develop them, and the severity and manifestation of these conditions can vary widely among affected individuals." (PMID 37511676, 2023). "Patients with transcription factor-linked MODY have different associated features based on their underlying aetiology, such as glycosuria in HNF1A-MODY, fetal macrosomia and neonatal hypoglycaemia in HNF4A-MODY, and developmental disorders of the kidney and multiple other organs in HNF1B-MODY." (PMID 28314945, 2017). "MODY are also associated with mutations in the genes encoding transcription factors like, hepatic nuclear factor 4 alpha (HNF4A), HNF1 homeobox A (HNF1A), pancreatic and duodenal homeobox 1 (PDX1), HNF1 homeobox B (HNF1B) and neurogenic differentiation 1 (NEUROD1)." (PMID 22399922, 2010). "Targeted gene panel sequencing for 16 genes, including major forms of MODY (HNF1A-, HNF4A-, GCK- and HNF1B-MODY), was performed." (PMID 39717432, 2025). "The most common MODY subtypes include GCK-(MODY2), HNF1A-(MODY3), HNF4A-(MODY3) and HNF1B-(MODY5), accounting for over 80% of all MODY cases." (PMID 40303944, 2025). "Although DKA is relatively rare, there are relevant reports, observed in some types of MODY, such as INS-, PDX1-, NEUROD1-, HNF1A- and HNF1B-MODY." (PMID 40303944, 2025). "Five out of eleven MODY genes were found affected, and these were GCK, HNF1B, HNF4A, PDX1, and RFX6." (PMID 39364395, 2024). "Mutations in the hepatocyte nuclear factor 1-α (HNF1A), 4-α (HNF4A), 1-ß (HNF1B/TCF2) and glucokinase (GCK) genes are responsible for most of the cases of MODY." (PMID 35406116, 2022). "Mutations in hepatocyte nuclear factor 1–α (HNF1A), hepatocyte nuclear factor 1–β (HNF1B), hepatocyte nuclear factor 4–α (HNF4A), and glucokinase (GCK) account for most diagnosed MODY cases." (PMID 36573710, 2022). "In this study, we focused on the four most common MODY genes (HNF4α, GCK, HNF1α, and HNF1β) and performed screening analysis of 45 Japanese pediatric patients who were between 2.8 and 17 years of age at diagnosis." (PMID 34746319, 2021). "To date, 14 disease genes for MODY are identified; most of them are transcription factors MODY1 (HNF4A), MODY3 (HNF1A), MODY4 (PDX1), MODY5 (HNF1B), MODY6 (NEUROD1/BETA2), MODY7 (KLF11), MODY8 (CEL), MODY9 (PAX4), MODY11 (BLK), and MODY14 (APPL1)." (PMID 31145732, 2019). "MODY and RCAD are autosomal dominant disorders, thought to be mediated by a haploinsufficiency-based mechanism due to a reduced amount of HNF-1α, HNF-1β or HNF-4α proteins." (PMID 19924231, 2009). "Similarly, in Norway, HNF1A accounted for 53% of MODY cases, GCK for 30%, HNF4A for 7.5%, and HNF1B for 5.6%." (PMID 41153735, 2025). "Most of our patients diagnosed with HNF1B-related MODY did not have renal disease (only one patient had renal agenesis and one family member that was not genetically tested had a history of renal cysts), and many had other traits of the mutation." (PMID 37511676, 2023). "We present an 18-year-old, non-obese female patient diagnosed with HNF1B-MODY." (PMID 38524636, 2024). "In contrast with other MODY types, HNF1B-MODY patients do not respond to sulphonylurea, they usually require early insulin therapy and nephropathy management may also be necessary." (PMID 34440499, 2021). "Secondly, since MODY is known to be a disorder of haploinsufficiency, we cannot rule out the possibility that there may also be species-specific differences in the dosage of the HNF1A, HNF1B and HNF4A gene products that are required for full function." (PMID 19924231, 2009).
MODY (continued). "Of the five 10−5 cutoff genes in MODY, HNF1A and HNF1B were absent in 10−8 set while the latter alone was missing from 10−7 and 10−6 gene lists." (PMID 23308243, 2013).
Renal cyst (100 papers, 2007 to 2026). A fluid filled sac in the kidney. "Renal/Gastrointestinal: HNF1B causes renal cysts and dysplasia; NEUROG3 leads to malabsorptive diarrhea." (PMID 41614934, 2026). "In patients with DM, the presence of cystic kidneys and elevated levels of liver enzymes can be used as predictors of an HNF1B mutation." (PMID 40901483, 2025). "The 17q12 deletion syndrome (OMIM #614527) is typically characterized by maturity-onset diabetes of the young type 5, renal cysts and Müllerian anomalies mainly associated with HNF1B haploinsufficiency (OMIM #189907)." (PMID 39766333, 2024). "This CNV can lead to 17q12 microdeletion syndrome, mainly manifested as renal cysts and diabetes syndrome caused by haploinsufficiency of HNF1B gene (chr17:34815072–36,192,489, OMIM#189,907)." (PMID 38951757, 2024). "Because hepatocyte nuclear factor-1β directly controls PKD2 transcription, the cystic kidney disease seen in patients with HNF1B variants mirrors ADPKD." (PMID 39291187, 2024). "The involvement of HNF1B pathogenic gene variants in renal disease was observed in pedigrees affected by MODY5: these patients often display renal cysts and renal function decline that preceded pancreatic dysfunction." (PMID 36672242, 2023). "Heterozygous intragenetic mutations or heterozygous gene deletions (17q12 microdeletion syndrome) of HNF1B are the cause of a multi-system developmental disorder, termed renal cysts and diabetes syndrome (RCAD)." (PMID 36969268, 2023). "Since the deletion encompasses HNF1B, which can involve renal cysts, the GREB1L variant would have been missed if the CMA had been performed before trio-ES." (PMID 37035737, 2023). "The renal phenotype in HNF1B-related renal cystic disease cases were variable, characterized by loss of corticomedullary differentiation and presence of scattered cysts." (PMID 37635794, 2023). "Histological analysis of a limited number of cystic kidneys from human fetuses carrying HNF1β mutations showed defective or delayed nephrogenesis characterized by a decrease in nephron structures labeled by either LTA, NKCC2, or UMOD." (PMID 35554666, 2022). "The HNF1B gene is expressed in the embryo in organs such as the kidney and the liver, and its heterozygous point mutations and small deletions cause renal cysts and juvenile or adult diabetes." (PMID 36034547, 2022). "HNF1B pathogenic variants are more frequently associated with hypo dysplasia and cystic kidneys and are rare in isolated lower urinary tract defects such as PUV and VUR, which were the most common diagnosis in the present study." (PMID 34979951, 2022). "Bilateral renal abnormality, renal cysts, simultaneous concomitant renal abnormalities and hypomagnesaemia were primary predictive for HNF1B mutations." (PMID 35346144, 2022). "Mutations in the gene encoding hepatocyte nuclear factor-1-beta (HNF1B) cause cystic kidney disease, and HNF1B has been shown to regulate expression of several cystogenic genes, including Pkhd1 and Cys1." (PMID 36710876, 2022). "Patients with HNF1β mutations often complicated with diabetes, renal cysts and loss of kidney function." (PMID 33512774, 2021). "The rare clinical subtype, MODY5, was confirmed by identifying variants in HNF1B for two index cases whose clinical presentations were consistent with the diagnosis of renal cyst and diabetes syndrome (RCAD)." (PMID 34373539, 2021). "Renal cysts were found to be the main clinical aspect with HNF1B mutations and the linkage of renal cysts with diabetes steered to the description of renal cysts and diabetes syndrome." (PMID 33580750, 2021). "Our analysis also detected two cases of MODY5 driven by the presence of HNF1β variants, who had evidence of renal dysfunction (renal cysts and dysplasia requiring renal transplantation in one case and increased levels of serum creatinine in the other)." (PMID 34373539, 2021).
Renal cyst (continued). "This review highlights the most common kidney cystic diseases during the neonatal period and a rare clinical case of HNF1B-associated disease." (PMID 35474932, 2021). "The HNF1B exon 4 p.E138K variant, in family 2, was detected in a Kuwaiti boy diagnosed shortly after birth with chronic renal failure due to bilateral cystic kidney disease." (PMID 34373539, 2021). "Renal malformations associated with HNF1B mutations vary and include renal cysts, renal hypodysplasia, renal agenesis, cystic renal dysplasia, and ureteral defects." (PMID 32164334, 2020). "In a Brazilian cohort, 28 patients with clinical suspicion of HNF1B-MODY due to hyperglycemia and renal cysts were evaluated and two positive cases of HNF1B gene mutations were found." (PMID 32528556, 2020). "The objective of our study was to verify the presence of variants in the HNF1B gene in a sample of the Brazilian population selected according to the presence of renal cysts and hyperglycemia." (PMID 31066763, 2019). "The recruitment of suspected cases of HNF1B gene mutations in Brazilians due to hyperglycemia and renal cysts presents two positive cases." (PMID 31066763, 2019). "In conclusion, the frequency of mutations in HNF1B gene in Brazilian patients selected for renal cysts and hyperglycemia was 7%." (PMID 31066763, 2019). "Renal cysts caused by HNF1B mutations are more heterogeneous; they can present as multiple, few, or no cysts, and some patients will enter into ESRD." (PMID 31056860, 2019). "Renal cysts are the most frequently observed clinical feature in HNF1B-associated renal disease, although the phenotype is very variable despite the single genetic aetiology." (PMID 30021660, 2018). "While renal cystic disease is a major manifestation of HNF1β mutations (65% of cases), considerable variation in renal phenotype exists." (PMID 29764441, 2018). "Mutations of PAX2 seem to be more frequently associated with renal hypodyplasia, while mutations in HNF1β are more frequently associated with cystic kidneys." (PMID 28398236, 2017). "While KIF12 has been implicated as a disease severity modifier of renal cystic disease via HNF-1B-induced transcription, its potential role in PRCA etiology is not immediately clear." (PMID 29156765, 2017). "In mice, kidney tubule-specific deletion of Hnf-1β resulted in decreased expression of miR-200s and caused renal cysts." (PMID 28587302, 2017). "Deletion of HNF1B is associated with renal cysts and maturity-onset diabetes type 5 while there is one report of a HNF1B duplication causing various renal abnormalities." (PMID 26123568, 2015). "Heterozygous germline mutations of HNF1B are associated with the renal cysts and diabetes syndrome (RCAD)." (PMID 25700310, 2015). "In the paediatric population, detection of antenatal renal abnormalities, renal hyperechogenicity and renal cysts were all more common in HNF1B mutation carriers (p = 0.0003, p = 0.0008 and p = 0.001, respectively)." (PMID 26022541, 2015). "Mutations in HNF1β have been identified in families with FJHN particularly those with atypical features such as renal cysts or other anomalies of renal development." (PMID 24886545, 2014). "Therefore, the discovery of renal cysts in a diabetic infant mandates HNF1B testing and screening for associated magnesium deficiency." (PMID 41614934, 2026). "Heterozygous mutations in HNF1B are associated with several congenital diseases including renal cysts, pancreatic hypoplasia, abnormal liver function tests, and urogenital tract abnormalities, suggesting that HNF1B is crucial for the normal development of these organs." (PMID 39915461, 2025). "However, the prenatal and postnatal phenotypes of seven individuals with renal cysts caused by a novel in-frame deletion, p.(Gly239del), within the HNF1B DNA-binding domain were previously reported." (PMID 39337310, 2024).